ATF6 (activating transcription factor 6)
Description:
[Cyclic AMP-dependent transcription factor ATF-6 alpha]: Precursor of the transcription factor form (Processed cyclic AMP-dependent transcription factor ATF-6 alpha), which is embedded in the endoplasmic reticulum membrane. Endoplasmic reticulum stress promotes processing of this form, releasing the transcription factor form that translocates into the nucleus, where it activates transcription of genes involved in the unfolded protein response (UPR). [Processed cyclic AMP-dependent transcription factor ATF-6 alpha]: Transcription factor that initiates the unfolded protein response (UPR) during endoplasmic reticulum stress by activating transcription of genes involved in the UPR. Binds DNA on the 5'-CCAC[GA]-3'half of the ER stress response element (ERSE) (5'-CCAAT-N(9)-CCAC[GA]-3') and of ERSE II (5'-ATTGG-N-CCACG-3'). Binding to ERSE requires binding of NF-Y to ERSE. Could also be involved in activation of transcription by the serum response factor. May play a role in foveal development and cone function in the retina.
Synonyms: ATF6A; ATP6alpha; ACHM7
Tractability: Antibody: UniProt predicts a signal peptide or a membrane-spanning region. PROTAC: UniProt records ubiquitination sites on it; ubiquitination databases record sites on it.
Gene: Protein-coding gene on chromosome 1 (161,766,261 to 161,977,574, forward strand). Ensembl gene ENSG00000118217.
Subcellular location: Endoplasmic reticulum membrane; Golgi apparatus membrane; Nucleus (Processed cyclic AMP-dependent transcription factor ATF-6 alpha)
Subcellular location (Human Protein Atlas): Golgi apparatus; Nucleoplasm; Cytosol; Endoplasmic reticulum; Nucleoli; Nucleoli fibrillar center; Primary cilium; Primary cilium tip
Pathways (Reactome):
Cellular responses to stimuli: ATF4 activates genes in response to endoplasmic reticulum stress; ATF6 (ATF6-alpha) activates chaperone genes; ATF6 (ATF6-alpha) activates chaperones
Immune System: Modulation of host responses by IFN-stimulated genes
Gene Ontology:
Molecular function: DNA-binding transcription activator activity, RNA polymerase II-specific; DNA-binding transcription factor activity; enzyme binding; identical protein binding; protein binding; protein heterodimerization activity; RNA polymerase II cis-regulatory region sequence-specific DNA binding; RNA polymerase II transcription regulatory region sequence-specific DNA binding; sequence-specific DNA binding; sequence-specific double-stranded DNA binding; transcription cis-regulatory region binding; DNA-binding transcription factor activity, RNA polymerase II-specific
Biological process: eye development; positive regulation of apoptotic process; positive regulation of ATF6-mediated unfolded protein response; positive regulation of autophagy; positive regulation of transcription by RNA polymerase II; response to endoplasmic reticulum stress; visual perception; ATF6-mediated unfolded protein response; endoplasmic reticulum unfolded protein response; ERAD pathway; protein folding; regulation of transcription by RNA polymerase II; signal transduction; regulation of ATF6-mediated unfolded protein response; regulation of DNA-templated transcription
Cellular component: endoplasmic reticulum; endoplasmic reticulum membrane; fibrillar center; Golgi apparatus; Golgi membrane; membrane; nucleolus; nucleoplasm; nucleus; RNA polymerase II transcription regulator complex; chromatin; cytosol; nuclear envelope
Genetic constraint (gnomAD): Loss-of-function variants: 32 observed, 48.72 expected, observed/expected ratio (o/e) 0.66, 90% interval 0.5 to 0.88. The upper end of that interval is the gene's LOEUF score, 0.88, which puts it in group 3 of 6, group 1 being the genes least tolerant of losing a copy. Missense variants: 528 observed, 578.52 expected, observed/expected ratio (o/e) 0.91, 90% interval 0.85 to 0.98. Synonymous variants: 216 observed, 218.37 expected, observed/expected ratio (o/e) 0.99, 90% interval 0.88 to 1.11.
Homologues: Orthologues: chimpanzee ATF6 (99% identical), macaque ATF6 (95% identical), pig ATF6 (93% identical), dog ATF6 (90% identical), guinea pig ATF6 (88% identical), rat Atf6 (86% identical), mouse Atf6 (85% identical), rabbit ATF6 (79% identical), tropical clawed frog atf6 (54% identical), zebrafish atf6 (44% identical), Drosophila melanogaster Atf6 (21% identical), Caenorhabditis elegans atf-6 (9% identical), and 4 more. Paralogues in human: ATF6B (33% identical), CREB3L3 (12% identical), CREB3L1 (12% identical), CREB3L4 (12% identical), CREB3L2 (11% identical), CREB3 (10% identical), CREM (9% identical), ATF1 (8% identical), CREB1 (8% identical).
Diseases named in the same sentence as ATF6 in open-access papers:
ATF6 is named in the same sentence as 268 diseases in open-access papers, as found by Europe PMC text mining. Sharing a sentence is not in itself a finding about the gene and the disease. The quoted sentences say what the papers report.
diabetes (53 papers, 2011 to 2025). "Prolonged ER stress and elevated ATF6 expression have also been linked to the development of diabetes mellitus (DM) as a result of pancreatic beta cell death." (PMID 40145401, 2025). "ATF6 also worsens endoplasmic reticulum stress induced vascular endothelial cells apoptosis which is implicated in diseases such as diabetes, atherosclerosis and ischemia." (PMID 36361847, 2022). "Our findings should be confirmed in prospective studies before ATF6 polymorphisms can be used to predict the risk of pre-diabetes in the Chinese population." (PMID 25302688, 2014). "The genetic variation in ATF6 is associated with pre-diabetes and has interactive effects with BMI on pre-diabetes in the Chinese Han population." (PMID 25302688, 2014). "The genetic variation in the ATF6 gene is associated with pre-diabetes and has interactive effects with BMI on pre-diabetes in the Chinese Han population." (PMID 25302688, 2014). "Both ATF6 and sXBP1 are closely linked with diabetes and atherosclerosis." (PMID 35889743, 2022). "In conclusion, this study systemically revealed that diabetes-associated hyperglycemia markedly deteriorated liver IR damage via activation of the ER stress-ATF6-CHOP signaling pathway, which subsequently inhibited β-catenin signaling and promoted TLR4-mediated inflammatory responses." (PMID 35289326, 2022). "Pharmacologic ATF6 activation has substantial potential for ameliorating tissue-specific defects in ER proteostasis implicated in diverse diseases including systemic amyloid diseases, ischemic heart disease, diabetes, and neurodegenerative disorders." (PMID 30084354, 2018). "We investigated whether genetic polymorphisms in ATF6 were associated with the risk of pre-diabetes in a Chinese Han population, and whether they had a synergistic effect with obesity." (PMID 25302688, 2014). "Association between pre-diabetes and SNPs at the ATF6 locus." (PMID 25302688, 2014). "However, our data suggests that the genetic variants in ATF6 are associated with pre-diabetes, the early stage of type 2 diabetes,and its related traits." (PMID 25302688, 2014). "Association analyses of haplotypes at the ATF6 locus with pre-diabetes." (PMID 25302688, 2014). "Several specific genes in this region, such as LMNA, NOS1AP and ATF6, were identified that they might confer risk for diabetes in some populations." (PMID 21211013, 2011). "Among these genes, ATF6 is a strong candidate by its biological function in endoplasmic reticulum stress and unfolded protein response, which linked insulin demand with beta cell failure and diabetes." (PMID 21211013, 2011). "In diabetes treatment, patchoulol inhibits crucial pathways, such as activating transcription factor 6 (ATF6), inositol-requiring enzyme 1 (IRE1), protein kinase RNA-like ER kinase (PERK), and Wnt/β-catenin." (PMID 40219102, 2025). "ER stress sensors, like p‐PERK, p‐IRE1α, and ATF6, participate in diabetes mellitus‐induced cognitive dysfunction." (PMID 39056330, 2024). "Lowering of blood glucose or treatment with a chemical chaperone (to improve ER protein folding) normalized sXBP1, ATF6 and CHOP levels, and reduced albuminuria and renal damage associated with diabetes." (PMID 38778209, 2024). "For example, the hyperactivation of IRE1α and ATF6 signaling pathways has been found to induce pancreatic cell death and exacerbate insulin resistance in the animal models of diabetes." (PMID 37152279, 2023). "The mRNA level of atf6 was increased significantly (2.35 ± 0.8-fold) during diabetes as compared with control." (PMID 36805334, 2023). "The protein expression of Atf6 was increased significantly during diabetes (25.12 ± 3.3%) as compared with control (2.6 ± 0.8%)." (PMID 36805334, 2023). "Constitutive expression of Atf6 was shown to improve cardiac function during ER stress–mediated cardiomyocyte apoptosis postinjury and during diabetes mellitus." (PMID 36805334, 2023).
diabetes (continued). "Our study showed an increase in the expression of ER stress markers Atf6 and Grp78 upon induction of diabetes." (PMID 36805334, 2023). "We have focused on the role of ATF6, PERK, and IRE1α as UPR-related genes responsible for monogenic diabetes or disease susceptibility in T2DM." (PMID 36613674, 2022). "While we demonstrate that increased cl-ATF6 α and sXBP-1 levels are critical for diabetes-induced senescence within plaques of diabetic mice and, in hyperglycaemia-exposed endothelial cells, the PERK/ATF4 arm was not studied." (PMID 35889743, 2022). "In contrast to DRlyp/lyp HCD rats, DRlyp/lyp HCD+Lp299v rats exhibited the greatest diabetes-free survival, the highest Atf6 expression, the lowest sXbp1 and Atf4 islet gene expression, and elevated ERAD-related activity." (PMID 36261888, 2022). "Diabetes-induced elevation of ATF6 level correlated with an enlargement of ER volume and a dilatation of cisterns that reflects the expansion of functional ER capacity." (PMID 35103058, 2022). "Insulin signalling upstream of p38; restores ATF6-related autophagy; insulin resistance, diabetes and Alzheimer’s pathophysiology." (PMID 35037854, 2022). "Recent studies suggest that zonisamide prevents diabetes-related dementia and cardiomyopathy by inhibiting upregulated expression of ATF6 and other ER stress marker proteins." (PMID 36077386, 2022). "CHOP is induced predominantly by the PERK/eIF2α/ATF4 signaling cascade associated with ER stress, as well as by the IRE1α/Xbp-1 signaling pathway and the ATF6α transcription factor in different pathological conditions, including diabetes." (PMID 34834808, 2021). "Future studies will be necessary to determine if modulation of ATF6α has therapeutic utility for the treatment diabetes." (PMID 34531828, 2021). "ATF6’s role in liver pathology is in agreement with previously reported links to fatty liver disease and diabetes." (PMID 31396860, 2020). "Fascinatingly, ATF6α both promotes and prevents the development of diabetes in mice as diet-induced obese ATF6α-knockout mice exhibit glucose intolerance due to pancreatic β-cell failure but are partially resistant to diet-induced insulin resistance." (PMID 29801500, 2018). "Ribosomal translation, insulin synthesis and processing, diabetes pathways and ATF6-controlled UPR chaperones gene sets were overrepresented among the genes upregulated in INS C96R cells." (PMID 30412052, 2018). "To further identify the underlying mechanism by which diabetes induces cardiac dysfunction and remodeling, we analyzed CHOP and ERS-activated signaling pathway effectors including PERK, eIF2α, ATF6, IRE1α, GRP78 and sXBP1." (PMID 29752433, 2018). "We found that diabetes caused a significant increase in the abundance of p-IREα, sXBP1, p-PERK, p-eIF2α, GRP78, ATF6 and CHOP in diabetic rats, whereas these effects were abolished by treatment with NAC." (PMID 29752433, 2018). "ATF6α-null mice display beta cell function impairment upon high fat diet but no such diet-induced insulin resistance; thus, ATF6α has ambivalent role on diabetes development." (PMID 29921793, 2018). "The role of ATF6α in the pathogenesis of human disease is also evident in diabetes, particularly in insulin-producing pancreatic β cells." (PMID 28860159, 2017). "In the present study, we demonstrated that not only CHOP but also other proteins in ER stress cascade, such as GRP-78, XBP-1, ATF-6, are elevated in the hippocampi of animal models of diabetes and primary hippocampal neurons exposed to high glucose." (PMID 27793043, 2016). "It is likely that the inability to fold the insulin intermediates and molecules related to insulin signaling and the subsequent elevation of ER stress-related molecules such as PERK, IRE1 alpha, and ATF6 are responsible for the impaired glucose homeostasis in diabetes." (PMID 38198459, 2024). "In addition to ATF6, previous studies have shown that diabetes-induced ER stress represses PGC-1α through CHOP expression induction." (PMID 35225153, 2022).
diabetes (continued). "The GWAS studies have identified SNPs in ATF6, the gene with no previously reported diabetes-associated pathogenic variants." (PMID 36613674, 2022). "Together, our data suggest that ORMDL3 may increase beta cell proliferation through ATF6 as a beta-cell compensation against diabetes." (PMID 31061237, 2019). "Together, our data suggest that ORMDL3 may increase beta cell proliferation through ATF6 as an early compensatory change in response to diabetes." (PMID 31061237, 2019). "After 6 months of diabetes, both Atf6 and Xbp1 expressions were upregulated in diabetic BMNCs." (PMID 29700294, 2018). "Some caution is recommended, however, as ATF6-mediated effects are controversial in the context of diabetes and may promote the survival of liver and squamous cell carcinomas." (PMID 29801500, 2018). "Diabetes-induced activation of ER stress signaling transducers ATF6 and PERK, and their downstream targets, including phospho-eukaryotic translation initiation factor 2α (p-eIF2α) and pro-apoptotic transcription factor CHOP were significantly attenuated by AS-IV treatment." (PMID 28761152, 2017). "Additionally, inhibition of IRE1 alone in models of diabetes led to hyper-activation of ATF6 that led to severe nephropathy." (PMID 27435960, 2016). "Interestingly, some reports demonstrated that some ATF6 variants are associated with type 2 diabetes and new onset diabetes after transplantation (NODAT), suggesting potential links between ATF6α and human diabetes pathophysiology." (PMID 24812634, 2014). "To verify our hypothesis that diabetes-induced hyperpermeability is related to endoplasmic reticulum (ER) stress, we investigated the levels of ER stress associated proteins including GRP78, ATF-6, PDI, CHOP and caspase-12 by western blot 1d after SCI." (PMID 28794417, 2017). "In conclusion, the results indicate that diabetes elevates lipid peroxidation and ROS production, activates the IRE1 and ATF6 pathways, and promotes a pro-apoptotic state leading to hippocampal neuronal damage." (PMID 40332364, 2025). "In experimental settings, ER stress can be induced in various tissues with diabetes in rats; when ER stress occurs, the expression levels of GRP78, CHOP, ATF6, p‐IRE1, sXBP1, and p‐PERK increase." (PMID 41280745, 2025). "Surprisingly, TUDCA was able to increase the expression of Atf6 and XBP1 and increased β-cells survival, reduced islet inflammation and thus lower diabetes incidence in mouse models of diabetes." (PMID 33613449, 2020). "In our results, CHOP, ATF6, and p‐IRE1 expression increased in diabetes‐induced testicular tissue." (PMID 41280745, 2025). "Moreover, other research reported on the beneficial outcomes of ATF6 pathway stimulation in facilitating pro-survival UPR, for the prevention of diabetes progression." (PMID 37020593, 2023). "Compared to the other two arm sensors (IRE1 and PERK) of ER stress, the ATF6 response in diabetes remains controversial due to the lack of receptors on ATF6." (PMID 34299638, 2021). "Moreover, in a T1D model mouse at the pre-diabetes stage, expression of UPR mediators, such as ATF6 and Xbp1, were downregulated." (PMID 31822470, 2019). "The protein levels of phosphorylated protein kinase RNA‐like ER kinase (p‐PERK), phosphorylated inositol‐requiring protein‐1α (p‐IRE1α), activating transcription factor 6 (ATF6), glucose regulated protein 78 (GRP78)and C/EBP‐homologous protein(CHOP) in kidney were significantly induced by diabetes." (PMID 30320493, 2018). "In type 1 diabetes, there is a progressive loss of ATF6α expression before the onset of diabetes in nonobese diabetic (NOD) mice as well as in pancreata from type 1 diabetic patients, suggesting that ATF6α protects β cells." (PMID 28860159, 2017).
diabetes (continued). "By using different murine models of diabetes (glucose-induced hyperglycemia mouse model; db/db mice and Akita mice) as well as β-cells isolated from pancreatic donors, they argue that mild UPR drives ATF6-induced proliferation of β-cells based on the insulin requirement." (PMID 33613449, 2020). "To date, no studies on the ATF6 gene specifically consider individuals with pre-diabetes." (PMID 25302688, 2014). "Interestingly, the protein level of ATF6 was increased after 3 months but not 9 months of diabetes." (PMID 29700294, 2018). "In the STZ model of diabetes in mice, neither AGE nor mLDL affected the levels of GRP78 or ATF6." (PMID 28127564, 2017). "We observed that ATF6, CHOP, ERN1, HSPA5, and ATF4 mRNA levels were significantly increased in tissues from subjects with diabetes, and this was supported by an increased expression of ATF6 and CHOP protein expression when compared with tissue from subjects without diabetes." (PMID 33028031, 2020).